CD63 (CD63 molecule)
Diseases named in the same sentence as CD63 in open-access papers (continued):
Sharing a sentence is not in itself a finding about the gene and the disease.
melanoma (110 papers, 2005 to 2025). A malignant, usually aggressive tumor composed of atypical, neoplastic melanocytes. "Collectively, these findings suggest that hypoxic exosomes drive CD63-dependent T cell exhaustion and loss of cytotoxicity, thereby linking CD63 to immune evasion in hypoxic melanoma microenvironments." (PMID 41573746, 2025). "Down-regulation of CD63 was associated with metastasis and neoplastic progression in melanoma and other tumors, as well as increased motility in tumor cells and enhanced matrix-degrading ability." (PMID 39273632, 2024). "We also show that the CD81+CD63+EV secretion signatures were associated with improved overall survival in melanoma (SKCM) patients." (PMID 34503207, 2021). "CD63 has also been implicated in the transport and regulation of other proteins in the progression of melanoma." (PMID 34638669, 2021). "Previous data from our laboratory have also shown that TIMP-1 associates with CD63 and β1-integrin to form a supramolecular complex on melanoma cell surface (4C11- and 4C11+ melanoma cell lines)." (PMID 34502227, 2021). "For instance, plasma exosomes bearing CD63, a classic exosome marker, and Cav1—which is elevated in prostate cancer and melanoma —are useful melanoma markers and are associated with poor prognosis in melanoma." (PMID 34496872, 2021). "The association of CD63 with the morphology of melanoma has been experimentally supported by a previous in vivo and in vitro study, in which the mechanism underlying such association was attributed to the negative linkage between CD63 signaling and EMT." (PMID 32541867, 2020). "Tspan8 was originally identified as a tumor-associated antigen by an antibody (CO-029), CD63 by a melanoma-associated antigen (ME491), CD151 was re-identified by an antimetastatic antibody, and CD82/KAI1 as a metastasis suppressor gene." (PMID 29946318, 2018). "In melanomas, high CD63 protein levels were associated with early stages of tumor progression and low levels with late disease stages, while CD63 mRNA expression levels were similar in pancreatic cancer and normal pancreatic tissue." (PMID 29523123, 2018). "Previous data from our laboratory showed increased Timp1 expression along melanoma progression and more important the assembly of a supramolecular complex containing Timp1, CD63, and β1-integrins associated with a more aggressive phenotype." (PMID 28430130, 2017). "High TIMP1 expression is associated with poor prognosis in melanoma, where it can bind to CD63 and β1 integrin, inducing PI3-kinase pathway and cell survival." (PMID 28430130, 2017). "In this context, CD63, a member of the tetraspanin family, was first identified as an antigen associated with early stages of human melanoma and as a binding partner of TIMP1 on the cell surface." (PMID 23522389, 2013). "Differential association among Timp1, CD63 and β1-integrins was observed in melan-a melanocytes, 4C pre-malignant melanocytes and 4C11- and 4C11+ melanoma cells." (PMID 23522389, 2013). "A morpholino knockdown strategy was used to investigate the role of cd63, a membrane protein associated with intracellular transport and a melanoma marker, in embryonic zebrafish." (PMID 21625559, 2011). "Tyrosine kinase activity in neutrophils has also been reported to be associated with CD63, the control signaling molecule used in this study, while serine kinase activity has been reported to associate with CD63 in melanoma cells." (PMID 19077207, 2008). "Immunohistochemistry studies have characterized CD63 as the stage-specific melanoma-associated antigen ME491." (PMID 16318634, 2005). "Finally, CD63, a well-known melanoma-associated antigen (also called “Melanoma-Associated Antigen ME491”), has a role in VEGFA signaling." (PMID 31921654, 2019). "We also demonstrated that Timp1 associates differentially with CD63 and β1-integrins along melanoma progression and that this association may be related to the induction of the PI3K signaling pathway." (PMID 28430130, 2017).
melanoma (continued). "Also the tetraspanin CD63, a well known marker of microvesicles, was associated with prometastatic pathways and evidenced together with Cav1 on plasma EXOs of melanoma patients." (PMID 26912358, 2016). "Finally, we also found loss of CD63 (member of the tetraspanin family), an event previously associated to advanced stages of melanoma." (PMID 26979459, 2016). "The association of serine protein kinase activity with CD63 may play a role in signaling by CD63 in melanoma." (PMID 16318634, 2005). "The current study suggests that serine protein kinase activity associated with CD63 may play a role in signaling by CD63 in melanoma cells." (PMID 16318634, 2005). "This study examined whether CD63 is associated with protein kinase and can transmit signals in melanoma cells." (PMID 16318634, 2005). "Similarly, the CD63, also known as melanoma-associated antigen ME491 or MLA1, is highly expressed at the tissue level in the initial stages of melanoma development but down-regulated in advanced metastatic lesions, suggesting that CD63 is likely a suppressor of tumor progression." (PMID 34065085, 2021). "Previous studies suggested that both CD63 and CD9 were associated with promotion or inhibition of melanoma progression in cell culture models." (PMID 40521809, 2025). "To investigate the regulatory mechanism of hypoxia on CD63, we first subjected the human melanoma cell line UMT2 cells to hypoxic treatment (1% O2, 12 h)." (PMID 41573746, 2025). "CD63 also acts as a suppressor of tumor progression, as elevated expression decreases melanoma cell motility and invasiveness." (PMID 39763976, 2024). "In the early phase of melanoma progression, CD63 was up-regulated; however, during disease progression, there is a down-regulation in CD63, increasing a metastatic potential." (PMID 39273632, 2024). "The identification of all the exosomes derived from all three melanoma cell lines was further confirmed by the exosomal markers CD63, CD9, and CD81 using immunoblotting." (PMID 39123364, 2024). "PEVs also influenced the melanoma spheroids’ own EV production by modifying their tetraspanin (CD63, CD9, and CD81) profiles." (PMID 39695652, 2024). "Fluctuations in TSG101 and CD63 were also observed in sEVs secreted by the RAB27A knockdown WM164 human melanoma cell line and the RAB27A knockout B16-F10 mouse melanoma cell line; however, this occurred without altering their total number." (PMID 39596498, 2024). "Meanwhile, an in-house study of melanoma reported that there was a higher level of CD63+ exosomes in cancer plasma, which was correlative with the level of caveolin-1, a component of caveolae." (PMID 35757760, 2022). "Subsequent studies demonstrated that CD63 was also involved in cargo targeting exosomes secreted by melanoma cells and in the biogenesis of exosomes in fibroblasts from patients with Down syndrome." (PMID 36435789, 2022). "Previous studies have reported the positive role of CD63 in the suppression of melanoma whereby it acted as a vital sign in patient assessment." (PMID 35046480, 2022). "The first study showed the tetraspanin-dependent mechanism of cargo sorted to ILVs, focusing on CD63, which is involved in endosomal sorting in melanoma cells." (PMID 36435789, 2022). "Melanoma-A consisted of CD63, PMEL, and S1000A1, while Melanoma-B consisted of S100B, FTH1, and AEBP1 expression." (PMID 33535416, 2021). "While a higher amount of CD63-positive and caveolin-1-positive exosomes were found in melanoma patients, detection based on caveolin-1-positive exosomes was more sensitive than that targeting CD63." (PMID 34575876, 2021). "Although CD63 was first identified to be expressed in early‐stage melanoma cells, it is reduced while tumour cells become more invasive, implying a negative role of CD63 in tumour invasiveness." (PMID 33277798, 2021).
melanoma (continued). "Similar procedures were applied for exosomes derived from melanoma cell cultures, including Spectradyne nCS1, flow cytometry (CD63), and TEM (University of Missouri Microscopy Core, Columbia, MO, USA) as described in Methods." (PMID 34638272, 2021). "Western blot analyses showed that the protein levels of both TYRP-1 and CD63 were higher in melanosomes derived from GIF-2209-treated B16F10 melanoma cells." (PMID 35011407, 2021). "In this study, it was confirmed that these melanoma cells use the TIMP1/CD63/β1-integrin complex to induce the activation of signaling pathways involving NF-κB and ERK precisely to promote resistance to Vemurafenib." (PMID 34502227, 2021). "Both CD9 and CD63 are important regulators of melanoma progression and metastasis, so we decided to use a human melanoma cell line for our studies." (PMID 34012515, 2021). "In histological studies, CD63 is related to melanoma malignancy and is differentially expressed in primary and metastatic lesions." (PMID 34222025, 2021). "Overexpression of CD81 partially rescued the infertility phenotype seen in CD9 KO mice and it was recently demonstrated that CD9 deletion in human melanoma cells was quickly compensated by CD63 expression upregulation." (PMID 34847198, 2021). "Both CD9 and CD63 are important regulators of melanoma progression and metastasis, and EVs have been reported to play a fundamental role in tumour metastatic niche formation." (PMID 34012515, 2021). "For instance, the high plasma levels of CD63 expression has been regarded as an indicator for chemoresistance in advanced melanoma." (PMID 33261145, 2020). "CD63 was the first characterized tetraspanin, which abundantly expressed in the early stage in melanoma, however, its level decreases in the process of malignant progression, so CD63 surface levels is negatively correlation with invasiveness." (PMID 33015133, 2020). "CD63+ exosomes were shown to be significantly increased in patients with melanoma and other cancers, therefore CD63 has been suggested to be a “cancer biomarker”." (PMID 31096692, 2019). "Exosomes expressing CD63 and cav1 have been described in large amount in plasma of melanoma patients." (PMID 29760588, 2018). "These analyses revealed a good linear behaviour, with very high r2 values and p values < 0.001, in the range between 1 to 15 ng for melanoma-EVs using anti-CD63 and anti-CD59." (PMID 28900146, 2017). "CD63+ exosomes were significantly increased in plasma of melanoma patients compared to healthy controls, while in a comparative analysis, CD63 was found enriched in exosomes derived from malignant cancer cells compared to those derived from non-cancer cells." (PMID 27766946, 2016). "Intracellular Av-SRho partially co-localized with CD107a and CD63 within intracellular vesicles, validating the use of Av-SRho as a tool to study melanoma LLE exposure." (PMID 26940455, 2016). "This analysis provided quantitative evidence of an antigen-dependent enrichment of melanoma cell CD63+ endosomal compartment at the synaptic area in a significant number of CTL/melanoma cell conjugates." (PMID 26940455, 2016). "Melanoma cells were defined as CD45−/CD31− cells co-expressing one or more melanoma-related antigens (CD63, CD146, CD166)." (PMID 24489649, 2014). "CD63 is abundantly expressed as a surface antigen in the early stage of melanoma, but its expression decreases with malignant progression, suggesting a negative correlation between CD63 surface levels and invasiveness." (PMID 25033048, 2014). "The percentage of CD63+ cells in melanoma cell lines was 39% in 607B cells, 42% in A375 cells, 87% in SK-Mel28 cells, and 89% in Mel-Juso cells." (PMID 24489649, 2014). "Relative expression of TIMP1 and CD63 in human metastatic melanoma cells was analyzed by real time PCR." (PMID 23522389, 2013).
melanoma (continued). "Our results show that Timp1 is assembled in a supramolecular complex containing CD63 and β1-integrins along melanoma genesis and confers anoikis resistance by activating PI3-K signaling pathway, independently of Akt phosphorylation." (PMID 23522389, 2013). "Reduction in CD63 expression, a marker identified in the malignant progression of human melanoma contributes to invasive and metastatic ability of human melanoma cells." (PMID 24132157, 2013). "Five from seven metastatic melanoma cells expressed significantly higher levels of TIMP1, and three from seven melanoma cell lines presented increased levels of CD63 compared to primary human melanocytes." (PMID 23522389, 2013). "They further determined that the number of caveolin-1 positive plasma exosomes was significantly greater than the number of CD63 positive exosomes in melanoma patients." (PMID 23056502, 2012). "CD63 was originally described as a marker in the early stages of melanoma progression since it was highly expressed in radial growth-phase primary melanomas." (PMID 21521534, 2011). "Consistently, plasma exosomes expressing CD63 (504±315) or caveolin-1 (619±310) were significantly increased in melanoma patients as compared to healthy donors (223±125 and 228±102, respectively)." (PMID 19381331, 2009). "We evaluated the levels of plasma exosomes expressing CD63 and caveolin-1 in melanoma patients (n = 90) and healthy donors (n = 58)." (PMID 19381331, 2009). "The current study also demonstrates that CD63 can transduce signals in melanoma cells and alter melanoma cell behavior." (PMID 16318634, 2005). "Melanoma cell adhesion to immobilized CD63 mAb required extracellular calcium, indicating that extracellular Ca2+ plays an important role in signaling by CD63 in these cells." (PMID 16318634, 2005). "In contrast, transfection of antisense CD63 cDNA into melanoma cells endogenously expressing CD63, resulted in increased cell motility and invasiveness in vitro." (PMID 16318634, 2005). "Over expression of CD63 partially suppressed malignant phenotypes of H-ras-transformed fibroblasts in vivo, and transfection of melanoma cell lines also suggested that CD63 can regulate melanoma cell function." (PMID 16318634, 2005). "A375SM melanoma cells were solubilized in a buffer containing Brij 58 as described in the Methods, and the solubilized material was immunoprecipitated by CD63 mAbs." (PMID 16318634, 2005). "We next examined the effects of extracellular Ca2+ on melanoma cell adhesion to immobilized CD63 mAbs." (PMID 16318634, 2005). "In this study, the properties of the adhesion of melanoma cells to immobilized CD63 mAb suggested that CD63 was capable of transmitting a signal that requires extracellular calcium." (PMID 16318634, 2005). "For CD63 and PMEL, the GO term GO:0006583 (melanin biosynthetic process) and its associated genes TYR and DCT were positively associated, suggesting activation of the tyrosine-to-melanin conversion pathway in the Melanoma-A region." (PMID 41279463, 2025). "Expanding upon the ceramide paradigm, CD63 has been implicated in the non-ESCRT-mediated sorting of premelanosome protein (PMEL) in human melanoma cells, where suppression of CD63 redirects PMEL towards ESCRT-mediated degradation." (PMID 40046812, 2025). "In melanoma pathogenesis, it confered anoikis resistance through β1-integrin and CD63 interactions." (PMID 41187171, 2025). "Bead-based multiplex analysis revealed the robust expression of the sEV tetraspanins CD9, CD63, and CD81 in addition to CD29 (Integrin beta- 1), the MSC-EV-specific markers CD44 (hyaluronic acid receptor) and MSCP/NG2 (melanoma‐ associated chondroitin sulfate proteoglycan)." (PMID 38764077, 2024). "In a small cohort comparison of four non-responders to four responders in human melanoma, the loss of CD63 and E-cadherin, the target of CD103, was associated with non-response in melanoma." (PMID 38562921, 2024).
melanoma (continued). "Importantly, the level of CD63 has been reported to be elevated in the plasma of leukemia, melanoma, and colorectal cancer patients." (PMID 33436891, 2021). "CD63, mapped to chromosome region 12p12→12q13, was initially reported as an early stage-specific marker of melanoma progression because of the strong-expression in dysplastic nevi and radial growth phase primary melanoma." (PMID 34222025, 2021). "However, in this melanoma cell line, compensatory upregulation of CD63 was already observed in these early passages, both by flow cytometry and Western‐blot." (PMID 34012515, 2021). "We previously developed a similar assay to detect and quantify plasma exosomes expressing Rab5B/CD63 or Rab5B/caveolin plasma exosomes and demonstrated that CD63+ exosomes or caveolin-1+ exosomes were significantly increased in melanoma and prostate cancer patients as compared to healthy donors." (PMID 32231660, 2020). "Indeed, in silico knockdown of CD63 expression in melanoma malignant cells resulted in the transition from compact to loose structures while overexpression of CD63 in HNC malignant cells resulted in compact structure." (PMID 32541867, 2020). "In addition, SFX significantly suppressed the levels of a transcription factor MITF, which can increase the expression of late endosomal proteins, such as RAB7 and CD63, and a main sEV secretion regulator, RAB27a, in melanoma cells." (PMID 30918259, 2019). "However, decreased levels of CD63 were found to enhance tumor motility and invasion in melanoma cell lines." (PMID 29523123, 2018). "For other types of cancer, the number of exosomes expressing CD63+ and/or caveolin-1+ are significantly increased in the plasma of patients with melanoma compared to that in healthy individuals, a finding that exhibits a higher detection sensitivity than that of conventional biomarkers." (PMID 28659795, 2017). "CD63+ and caveolin-1+ are mutually related, and in conjunction with other biomarkers, such as p-Met, TYRP2, HSP70, HSC70, and VLA-4, this association increases the predictive accuracy of early diagnosis and prognosis of melanoma." (PMID 28659795, 2017). "Moreover, we have shown that, in human metastatic melanoma cells, Timp1 and CD63 expression are increased and positively correlated with colony formation capability, strengthening the possible role of Timp1 in human melanoma genesis." (PMID 28430130, 2017). "FACS analysis showed that melanoma cells exhibited higher constitutive CD107a and CD63 surface expression when compared with conventional target cells, suggesting that melanoma cells might exhibit a constitutively active secretion of LLE vesicles." (PMID 26940455, 2016). "Enhanced expression of the adhesion markers CD29, CD49c, CD56, CD63 and CD107a on CD45− melanoma cells and loss of T-cell-related immunity is implicated in melanoma progression following a prolonged period in which metastatic disease has remained clinically silent/undetected." (PMID 24435119, 2014). "Several studies reported alteration in CD63 expression along melanoma progression." (PMID 23522389, 2013). "In conclusion, our data demonstrate differential interaction among CD63, Timp1 and β1-integrins between normal and melanoma cells and that this binding may regulate essential processes for tumorigenesis such as anoikis resistance." (PMID 23522389, 2013). "Preventing adhesion to the substrate could result in changes in the structure and composition of lipid rafts, glycosphingolipid-cholesterol-enriched microdomains, affecting Timp1/CD63/β1-integrin complex assembly along melanoma development." (PMID 23522389, 2013). "CD63 plays a role in the regulation of cell motility in melanoma cells and is involved in cell adhesion events, and strongly expressed on the cell surface in the early stage of malignant melanoma but weakly in the more advanced stages." (PMID 21521534, 2011).